RNU6-493P (RNA, U6 small nuclear 493, pseudogene)
Gene: Small nuclear RNA gene on chromosome X (80,900,757 to 80,900,864, forward strand). Ensembl gene ENSG00000212623.
Homologues: Orthologues: chimpanzee U6 (82% identical), macaque U6 (81% identical). Paralogues in human: RNU6-144P (76% identical), RNU6-869P (76% identical), RNU6-1020P (75% identical), RNU6-16P (75% identical), RNU6-403P (75% identical), RNU6-45P (75% identical), RNU6-46P (75% identical), RNU6-480P (75% identical), RNU6-732P (75% identical), RNU6-1075P (74% identical), RNU6-1124P (74% identical), RNU6-12P (74% identical), and 1285 more.